CD4 (CD4 molecule)
Diseases named in the same sentence as CD4 in open-access papers (continued):
Sharing a sentence is not in itself a finding about the gene and the disease.
tumor (continued). "Furthermore, among all kinds of immunocytes, the existing evidence supports the crucial role of activated B cell, activated CD8+ T cell, central memory CD4+ T cell and type 1 helper cell for BC prognosis associated with the anti-tumor immune surveillance and regulation." (PMID 40281780, 2025). "Similarly, high HLA-DR expression on tumor cells in laryngeal squamous cell carcinoma has been linked to better prognosis and potential response to anti-PD-1/PD-L1 therapy, possibly through increased CD4+ tumor-infiltrating lymphocytes." (PMID 41306529, 2025). "The CIBERSORT analysis revealed that the risk score was negatively correlated with CD8+ T cells, and resting memory CD4+ T cells, which may impair effective immune surveillance, suggesting that patients with higher risk scores tend to have an immunosuppressive tumor microenvironment." (PMID 41080752, 2025). "Moreover, Tregs were shown to have a closely associated spatial relationship with both CD8+ and CD4+ T cells in imTLS, suggesting Tregs may impede local anti-tumor immunity in the TME." (PMID 40335494, 2025). "It was found that EVs enhanced the systemic delivery of the OVs, resulting in improved tumor-selective delivery, a peritumoral immune response associated with the targeted delivery of the virus, enhanced immunogenicity, and the infiltration of CD4+ and CD8+ T cells." (PMID 40725148, 2025). "In our study, PICs displayed CD4+ T cell-associated protein features and accompanying molecular and morphological patterns, such as HLA-DR expression in patient P1 and elevated cleaved Caspase-3 in both patients, that align with phenomena reported in immune-tumor interactions." (PMID 41301033, 2025). "Notably, the proportion of CD4+ cytotoxic T lymphocytes showed the largest increase in the combination therapy group, highlighting a potential mechanism underlying the enhanced anti-tumor effect." (PMID 41309527, 2025). "CXCL13 gene expression correlated with TLS presence.CXCL13-producing CD4+ T cells are involved in the early stage of TLS formation.TLS formation was associated with CXCL13-producing CD4+ T cells & TLS facilitated the coordinated anti-tumor response of cellular & humoral immunity in OC." (PMID 40475770, 2025). "Since reduced CD4 + T cell counts are associated with decreased levels of pro-inflammatory cytokines such as IL-2 in the circulation, we assume that despite an increase in some NK cell subsets, these effector cells are unable to mediate protective anti-tumor immunity in advanced tumors." (PMID 40783506, 2025). "Infiltrating lymphocytes such as CD8+ and CD4+ T cells, Tregs, TAMs, tumour‐associated neutrophils (TANs), myeloid‐derived suppressor cells (MDSCs) and natural killer (NK) cells can exhibit antitumour or pro‐tumour effects, depending on the context, thereby influencing tumour progression." (PMID 39924620, 2025). "In addition, TCR repertoire analyses have revealed considerable heterogeneity among intratumoral Treg cells, including those that are specific for tumor-associated antigens or neoantigens or those that have differentiated from previously activated conventional CD4+ T cells." (PMID 40468052, 2025). "During cancer treatment, dogs often receive corticosteroids, which, while helpful in some cancer types or relieving tumor-associated symptoms, may also suppress CD4 and CD8 T cell activation and induce leukopenia, potentially diminishing the efficacy of ICI therapy." (PMID 40342421, 2025). "Key effector cells—including CD8+ T cells, CD4+ T cells, Mast cells, eosinophils and neutrophils—showed significant negative correlations with risk scores, while immunosuppressive populations such as regulatory T cells (Tregs), tumor-associated fibroblasts and macrophages were positively correlated." (PMID 40963600, 2025).
tumor (continued). "Furthermore, we found that the expression of NTN1 and its receptors in several cancers, including BLCA, KIRC, READ, and COAD, was closely associated with tumor-infiltrating immune cells such as CD4 + T cells, CD8 + T cells, macrophages, neutrophils, and dendritic cells." (PMID 41407823, 2025). "Moreover, depletion of bulk Treg cells may consequently induce conventional CD4+ T cells to express the immunosuppressive cytokine IL-10, causing a paradoxical immunosuppressive barrier to anti-tumor immunity." (PMID 40468052, 2025). "Additionally, elevated lactate dehydrogenase (LDH) activity in tumor cells consumes glucose within the tumor microenvironment, causing energy deprivation in CD4+ T cells and elevating the expression of checkpoint molecules such as PD-1, consequently impairing their functionality." (PMID 40936705, 2025). "Second, OV-mediated oncolysis of tumor cells initiates the release of tumor-associated antigens, cellular danger-associated molecular pattern signals, and cytokines that promote the maturation of antigen-presenting cells and activate antigen-specific CD4 and CD8 T cell responses." (PMID 38595813, 2024). "Interestingly, Gls1 deletion alone led to an immune suppressive tumor microenvironment facilitated by increased cancer-associated fibroblasts (CAF) & IL2_STAT5 signaling while simultaneously decreasing inflammatory & activated CD4 T cell responses." (PMID 38769385, 2024). "Moreover, across these 4 types of solid tumor, CD4+ effector T cells and apCAFs exhibit a co-localized spatial distribution, indicating that apCAFs may be associated with anti-tumor effects by promoting the survival of CD4+ T cells." (PMID 38903527, 2024). "Therefore, we propose that CD4+ T cell therapy may prevent acquired tumor resistance caused by impaired HLA class I antigen processing and presentation." (PMID 38412034, 2024). "Furthermore, it may contribute to an immunosuppressive tumor microenvironment by activating tumor-associated macrophages and Th2 polarization of CD4+ T-cells." (PMID 38082056, 2024). "Additionally, the reduced number of DNT cells may be associated with the decreased function of effector CD4+T cells with CTLs in tumor patients." (PMID 38263363, 2024). "In BPR20 tumors treated with ARG2i/COX2i/NOS2i, an increase in CD45+ immune cell infiltration into the tumor was observed, corresponding with increases in gene transcripts associated with immune cell-mediated tumor growth control and inflammation (e.g., Ccl21a, Fasl, Cd8b1, Cd40, Cd4, Cxcl11)." (PMID 38312842, 2024). "The BRAF-mutant tumor samples also contained elevated levels of macrophages, mucosal-associated invariant T cells, cancer-associated fibroblasts, hematopoietic stem cells, common myeloid progenitors, myeloid dendritic cells, and CD4+ T cells compared to the BRAF-wild-type tumor samples." (PMID 39336897, 2024). "IFN-γ signaling is particularly important in tumor infiltration and functions by polarizing tumor-associated macrophages (TAMs) from an M2-immunosuppressive type to an M1-pro-inflammatory type; however, it also reduces the presence of CD4 and CD8 T cells in the TME via MIF/CD74 signaling." (PMID 38732068, 2024). "Therefore, it appears that apCAFs may be associated with anti-tumor immune responses, possibly by promoting the survival of CD4+ T cells through C1Q molecules expression in these solid tumor types." (PMID 38903527, 2024). "Therefore, the influence of the deficiency of DCs on the population sizes of CD4+Foxp3+ Treg cells and Teff cells may regulate the direction of the adaptive anti-tumor immune responses that control the development of tumors." (PMID 39206204, 2024). "The tumour-associated stromal cell compartment contains immune cells as antigen-processing cells as macrophages (M1, M2), and antigen- presenting cells as dendritic cells (DC), and finally antigen-specific cells as T cells, both CD4 and CD8 subsets and B cells." (PMID 38576614, 2024).
tumor (continued). "Background/Objectives: The MHCII-dependent, CD4+ T-cell zwitterionic polysaccharide PS A1 has been investigated as a promising carrier for vaccine development because it can induce an MHCII-dependent CD4+ response towards a variety of tumor-associated carbohydrate antigens (TACAs)." (PMID 39772036, 2024). "Transcriptional analysis showed increased expression of cytotoxic genes such as NK markers and Granzyme A in intestinal IEL CD4+ T cells in aged mice, suggesting that intestinal CD4+ T cells in aging individuals may respond to the increased tumor risk by increasing their cytotoxic activity." (PMID 38327516, 2024). "This tendency may be due to the crosstalk between myeloid-derived suppressor cells (MDSC) and tumor-associated macrophages (TAM) promoting CD4 T cell differentiation into T+H2 phenotype with IL-4 production, which in turn induces the development of M2 macrophages." (PMID 37006257, 2023). "Due to the GSEA-indicated enrichment in gene sets associated with CD4 + T cell activation, lymphocyte activation, and leukocyte proliferation in Braf/Pten/Cxcr2−/− tumors, we then evaluated the immune cell infiltrate between Braf/Pten/Cxcr2WT and Braf/Pten/Cxcr2−/− tumor-bearing mice." (PMID 37270599, 2023). "Patients at high- m6APR_Score group had significantly poor prognosis and we hypothesized that T Cell CD8 and T Cell CD4 were activated in patients at high prognostic risk and that immune checkpoints derived from T cells might trigger immune escape of tumor cells by blocking immune cell function." (PMID 37596597, 2023). "We hypothesized that IL-6 levels might be associated with the state of anti-tumor immunity related to the treatment effect of eribulin, and so we analyzed the peripheral blood fractions for helper (CD4+) and cytotoxic (CD8+) lymphocytes, Tregs and MDSCs involved in tumor immunity at baseline." (PMID 37733188, 2023). "Moreover, PD-1/PD-L1 expression and CD4+ intraepithelial lymphocytes (IELs) are associated with tumour progression in patients possessing the wild-type XRCC1, suggesting that XRCC1 expression is correlated with patient survival, tumour-infiltrating lymphocytes, and immune marker expression." (PMID 37679817, 2023). "Moreover, we found both USF1 and PTBP1 expression were significantly associated with the infiltration levels of CD4+ Th1 cells that could function in pro-tumor immunity." (PMID 37900187, 2023). "Additionally, XCELL results demonstrated a notable decrease in CD4+ Th1 cells, a key cell for generating long-lasting anti-tumor immune responses, in the high-risk group, which may be a possible factor for the poorer prognosis." (PMID 37629096, 2023). "Furthermore, since CD4+ T cells are critical for tumor surveillance and suppression, this indicates that reduced CD4+ T cells could lead to abnormal cell signaling that causes liver tumorigenesis." (PMID 37623879, 2023). "Besides, we further investigated the relationship between the risk score and the immune infiltrate in the TCGA HCC cohort and found that the high-risk group has a higher level of immune cells in the tumor microenvironment, such as B cells memory, T cells CD4 memory resting and mast cells activated." (PMID 37014321, 2023). "Similarly, the loss of miR-17-92 in CD4+ T led to tumor immune evasion." (PMID 37671150, 2023). "Furthermore, tumor-associated CD4+ T cells can also release IL-6 in ccRCC." (PMID 37190141, 2023). "In vitro co-culture experiments and immunohistochemical staining have shown that tumor-associated neutrophils decreased the proliferation of CD4+ T cells and upregulated the expression of programmed cell death protein 1, which might promote an immunosuppressive cancer environment in GC." (PMID 36983614, 2023).
tumor (continued). "Tumor immune microenvironment analysis showed that the high-risk score of the prognostic model was positively correlated with M2 macrophages, cancer-associated fibroblast, hematopoietic stem cell, stromal score, and negatively correlated with NK cell, cytotoxicity score, B cell, and T cell CD4+Th1." (PMID 37144238, 2023). "This indicates that the CD4+ Treg cell ratio may be associated with tumor progression." (PMID 37238744, 2023). "CD39+CD4+ T cells which upregulate genes associated with an active Treg phenotype (CD25) also predicts poor outcome while high densities of CD39+CD103+CD8+ T cells in the tumor nest which upregulate cytotoxicity—and tissue residency genes, are linked to improved 5-year survival." (PMID 37648263, 2023). "Compared to controls, HPV+PFPS+DCs significantly inhibited tumor growth in both the early and late phases, which was significantly associated with an elevated activation status of CD4+ and CD8+ T cells, suggesting that PFPS may be a potential adjuvant for the DC vaccine." (PMID 37876967, 2023). "Apoptotic or necrotic tumour cells release intracellular molecules and antigens as well as damage-associated molecular patterns that recruit both adaptive and innate immune cells (dendritic cells [DCs], macrophages, CD4+ and CD8+ T cells, and natural killer [NK] cells)." (PMID 38567060, 2023). "Furthermore, vaccination within tumor-associated exosomes loaded T-cells could counteract CD4 + CD25 + Treg cell-mediated immunosuppression and trigger CTL long-term memory to stimulate immune responses." (PMID 37497408, 2023). "When patients are vaccinated with synthetic tumor-specific or tumor-associated peptides or combinations of peptides, these peptides are presented on human leukocyte antigen (HLA) molecules on the cell surface, inducing and activating CD4+ and CD8+ T cells, resulting in powerful therapeutic effects." (PMID 36092724, 2022). "Recently, CD4 T cells displaying a cytotoxic gene signature were reported in children with high-risk neuroblastoma and were associated with a putative protective effect that declined over time due to the progressive formation of an immunosuppressive tumour microenvironment." (PMID 35572552, 2022). "Similarly, autophagy in myeloid-derived suppressor cells’ (MDSCs) inhibits the antitumor immune responses, as evidenced by the report that autophagy-deficient monocytic MDSCs result in efficient activation of tumor-specific CD4+ T cells and improved antitumor immunity." (PMID 36003368, 2022). "In addition, immunosuppressive regulatory T cells (Foxp3+ CD4+) increase with time in both models, but only E0771 tumors display an early growth period when a majority of tumor-associated CD4+ T cells are immunostimulatory, resulting in a more favorable environment for CPA responses." (PMID 36187936, 2022). "Similarly, activin A reportedly reprogrammed pre-tumorigenic macrophages to a tumor-associated phenotype, promoted conversion of CD4+CD25− naïve T cells into regulatory T cells, and induced a pro-fibrotic transcriptome in fibroblasts, thereby transforming them into myofibroblasts." (PMID 36434305, 2022). "Moreover, we demonstrated that tumor-specific CD4+ T cells also became exhausted during tumor progression and that PD-L1 administration caused a proliferative burst of the tumor-specific CD4+ T cells, which could eliminate lung metastasis." (PMID 35784297, 2022). "Results showed that B cells, CD4+T cells, macrophages, and myeloid DC cells were less abundant in the high-risk group, which suggested that cell cycle checkpoints-related genes may promote tumor progression by suppressing anti-tumor immune system activation." (PMID 35646074, 2022). "However, by plotting tumor cell frequencies against the fraction of immune cell subsets, we found a significant positive association between tumor burden and increased frequencies of CD8 T cells and Tregs, whereas the frequency of CD4 T cells was inversely associated with tumor burden." (PMID 34165864, 2022).
tumor (continued). "The results indicated that high-risk group was more positively correlated with tumor-infiltrating immune cells such as B cells, cancer associated fibroblast, endothelial cell, monocyte, macrophages, and myeloid dendritic cell, whereas they were negatively correlated with CD4+ T cells." (PMID 35574385, 2022). "However, the increase of CD8+ cells was the basis of cellular immune damage, and the decline of CD4+ cells could cause immune escape of tumor cells." (PMID 36118825, 2022). "Furthermore, CD4+ T cells and macrophages infiltrated in GC samples could decrease the tumor purity and low tumor purity in GC was associated with an unfavorable prognosis and the immune-evasion phenotype." (PMID 36686788, 2022). "Although the expression of VISTA on CD4+ T cells has been implicated in tumor progression in a recent study, it should be cautiously assumed based on the small patient numbers that the expression of VISTA on CD4+ T cells may be a novel clinical prognostic parameter for NSCLC." (PMID 35122478, 2022). "This strategy will allow for the identification of TCR sequences within the DP CD4+ Th TILs that recognize mutated or shared tumor antigens bound to MHC class II molecules that could then be used in TCR engineering for personalized therapies in patients with cancer." (PMID 35439168, 2022). "Hence, vaccination-induced downregulation of CD40L may result from decreased activation levels of CD4+ T cells associated with low tumor burden in vaccinated groups." (PMID 36432733, 2022). "Likewise, in HTB-1 bladder, HPV+ SiHa cervical, and MDA-MB-231 triple negative breast cancer models in PBMC-humanized NSG mice, bintrafusp alfa achieved significant tumor growth control linked with increased tumor infiltration IFN-γ producing CD4+ and CD8+ T cells." (PMID 36159809, 2022). "Collectively, these results indicate that a low dose of Salmonella could enhance the immunogenicity of MC38 tumors through an increase in the antigen presentation potential of tumor-associated monocytes as well as the extent of CD4+ T cell infiltration into the tumor microenvironment." (PMID 36605208, 2022). "Unfortunately, daily 75 mg/kg BAY1082439 treatment led to significantly decreased tumor- and spleen-associated CD45+, CD8+ T and CD4+ T cell numbers, which could be detrimental for T cell-mediated anti-tumor immunity even if cancer cell-intrinsic immunosuppression could be alleviated." (PMID 35013322, 2022). "Moreover, EZH2 inhibition substantially increased the intratumoral trafficking of activated CD8+ and CD4+ T cells (decreasing the relative number of regulatory T cells, Tregs) and increased M1 tumor-associated macrophages (TAMs) (decreasing the tumor-promoting M2 macrophages)." (PMID 34830196, 2021). "Interestingly, it has been demonstrated that CD3ζ chain downregulation caused by tumor‐derived MDSCs overexpressing Arg1 might be more detrimental for CD4+ T cells than CD8+ T cells." (PMID 34037806, 2021). "In addition, HIF-1ɑ also promotes a tumor-tolerant environment, reducing the infiltration of CD4+ and CD8+ T-lymphocytes and tumor-associated macrophages (TAMs), increasing the differentiation of T-lymphocytes into T-helper 17 (TH17) cells and modulating TAM polarization." (PMID 33423689, 2021). "First, lymphodepletion causes amount decrease in CD4+ regulator T cells, which holds key role in keeping periphery tolerance and suppression of anti-tumor immune response, with the low amount or absence of these cells, the immunotherapy is able to induce T cells’ anti-tumor response." (PMID 34837913, 2021). "CD4+ T‐cell suppression or dysfunction has been reported as the mechanism causing cancer escape; the Th2 response was associated with tumor immune evasion in mouse studies, known to be particularly powerful in promoting tumor progression and suppressing antitumor immune responses." (PMID 34606634, 2021).